CD36 (CD36 molecule (CD36 blood group))
Diseases named in the same sentence as CD36 in open-access papers (continued):
Sharing a sentence is not in itself a finding about the gene and the disease.
steatosis (continued). "Moreover, previous studies confirmed that overexpression of CD36 led to steatosis in mice, and liver-specific knockout of CD36 reduced lipid content in mice fed with HFD." (PMID 34675931, 2021). "Via suppressing the role of the cd36 gene, the steatosis in zebrafish larvae can be rescued." (PMID 33513687, 2021). "Knockout of Cd36 has been shown to protect against diet-induced steatosis and NASH13." (PMID 34893641, 2021). "It has been proposed that hepatic PPARγ and CD36 may increase the uptake of lipids by hepatocytes which could promote steatosis in mice fed a MCD diet." (PMID 32411189, 2020). "Accumulated CERs may intensify steatosis by the activation of the protein kinase C ζ (PKCζ) pathway resulting in CD36 translocation to the plasma membrane and an increase FA uptake." (PMID 32796572, 2020). "Consistent with the inhibition of steatosis, GA suppressed the expression of CD36, FATP2, and ACCα." (PMID 32443660, 2020). "In fact, the adenovirus-mediated overexpression of hepatic CD36 led to steatosis in chow-fed mice, and hepatocyte-specific knockout of CD36 reduced hepatic lipid uptake and steatosis in a model with diet-induced steatosis, which support the steatogenic role of hepatocyte CD36." (PMID 32411189, 2020). "Adenovirus-mediated overexpression of CD36 enhances hepatic fatty acid uptake and fat accumulation, while liver-specific knockout of CD36 decreases hepatic lipid levels in both genetic and diet-induced steatosis." (PMID 29936596, 2018). "Concomitant with the increase in PPARγ2 expression, overexpressing JMJD2B stimulated the expression of hepatosteatosis genes including fatty acid uptake-associated genes CD36, FABP4 and lipid droplet-associated genes PLIN2, CIDEC in HepG2 cells, which are known PPARγ2 steatosis target genes." (PMID 30214048, 2018). "In vitro steatosis induced cell surface CD36 expression in each analyzed group of cells." (PMID 30442920, 2018). "Consistently, nine genes in the fatty acid metabolism, phospholipidosis and steatosis pathways including Acot2, Ugt2a1, Cd36 and Retn were upregulated in the cirrhotic liver post SPION injection accompanied with elevated Tgfb1 and sodium bile acid cotransporter (Slc10a1) of the cholestasis pathway." (PMID 27357559, 2016). "Interestingly, cluster differentiation 36 (Cd36), a fatty acid transporter gene involved in steatosis development, was identified as the top regulated gene in this module." (PMID 27470139, 2016). "Based on these results, we propose that VPA may enhance OLA-induced hepatocyte steatosis through the upregulation of PPARγ- and CD36-dependent lipid uptake, TAG synthesis, and lipid droplet formation." (PMID 27034954, 2016). "Furthermore, we assessed the effect of rapamycin, an mTOR-specific inhibitor, on hepatic CD36 translational efficiency and steatosis under inflammatory stress in vitro and in vivo." (PMID 25048611, 2014). "Notably, experimental amelioration of steatosis in mice was accompanied by hepatic CD36 downregulation." (PMID 25310357, 2014). "Thus, a role for PPARγ as an inducer of steatosis in hepatocytes has been suggested, and our results also show upregulation of PPARγ mRNA and its target gene CD36 in liver by the HF–HS diet." (PMID 22762794, 2012). "In addition, the decrease in steatosis itself may also secondarily suppress CD36 expression by suppressing PPARγ, a transcriptional activator of CD36." (PMID 41178716, 2025). "Notably, PDE4D overexpression in mouse liver increased CD36 expression, suggesting that the PDE4D‐CD36 axis might contribute to the hepatic steatosis observed in Atp8b1 mutant mice." (PMID 40851490, 2025). "However, PEA administration could obviously attenuate the expression of both ACC1 and CD36, suggesting that the anti-steatosis effect of PEA is partly dependent on the inhibition of ACC1-mediated lipogenesis and CD36-mediated fatty acids uptake." (PMID 34712137, 2021).
steatosis (continued). "Therefore, based on their known actions on lipid metabolism and homeostasis in the liver, PPARγ and CD36 may increase lipid uptake in hepatocytes and contribute to the progression of steatosis and steatohepatitis induced by MCD diets." (PMID 32411189, 2020). "The lack of steatosis in B-13 cells in response to either fatty acids or T0901317 may be associated with a lack of CD36 and LXR expression respectively." (PMID 28552552, 2017). "Cd36 is another target gene of PPARγ that could promote steatosis." (PMID 27973423, 2016). "The steatosis induced in these mice is likely due in part to induction of the fatty acid transporter Cd36 by peroxisome proliferator-activated receptor γ (PPARγ), as treatment with a PPARγ antagonist reduces the expression of liver Cd36 and decreases liver triglyceride content." (PMID 26959237, 2016). "Contrary to the phenotype observed in Eva1a-LKO mice, Eva1a overexpression suppressed both transcription and expression of CD36, while enhancing those of CPT1A, thereby mitigating steatosis in the livers of ob/ob mice." (PMID 41306774, 2025). "Clinical studies show that hepatic CD36 elevation drives fat accumulation in NAFLD patients, and it correlates with steatosis severity." (PMID 40725208, 2025). "Hepatic expression of CD36 tends to be elevated in conditions of NAFLD, and CD36 overexpression can promote lipogenesis and steatosis." (PMID 40458821, 2025). "The expression level of CD36 was positively correlated with that of YBX1 in the liver tissues of MASLD patients and in an in vitro steatosis model." (PMID 40083711, 2025). "The study suggested that the Liver X Receptor (LXR) was the primary factor contributing significantly to the combined effect on steatosis, since synergistic effects were evidenced only on LXR target genes, namely Cyp7a1 and Cd36." (PMID 38891072, 2024). "Elevated CD36, IGFBP1 (insulin-like growth factor–binding protein 1), and chemokine (C–C motif) ligand 2 (CCL2) expression leads to steatosis and inflammation in the Wtap-HKO livers." (PMID 37777158, 2023). "The fatty acid translocase CD36 was recognized as a newly discovered transcriptional target gene of AhR, responsible for mediating the development of steatosis." (PMID 38067179, 2023). "Hepatic disruption of fatty acid translocase CD36 in JAK2L livers has been shown to lower triglyceride (TG), diacylglycerol (DAG) and cholesterol ester (CE) content, significantly improving steatosis." (PMID 36835287, 2023). "However, the dramatic loss of adipose tissue induced by MCD diets may reduce the net flux of fatty acids from adipose tissue to the liver over time, and as a consequence, the potential contribution of hepatocyte CD36 to the development of MCD-induced steatosis." (PMID 32411189, 2020). "They believed that there is a new link between the central nervous system and the liver, and PRL improves steatosis of the liver through PRLR and fat/CD36." (PMID 32477263, 2020). "Treatment with BAR502 caused a ≈10% reduction of b.w., increased insulin sensitivity and circulating levels of HDL, while reduced steatosis, inflammatory and fibrosis scores and liver expression of SREPB1c, FAS, PPARγ, CD36 and CYP7A1 mRNA." (PMID 28202906, 2017). "In mouse models, CD36 has been established as a common target gene of LXR, PXR and PPARγ in promoting steatosis." (PMID 23874477, 2013). "In pre‐transplant PFIC1 liver, on the other hand, CD36 expression was not induced, which is consistent with the absence of steatosis." (PMID 40851490, 2025). "Both high-fat diets induced steatosis and inflammation as evidenced by liver TAG content and histology and mRNA expression of inflammation markers including F4/80, Mcp-1 and Cd36." (PMID 38439535, 2024).
steatosis (continued). "At the gene expression level, the lipid biosynthetic genes Fasn and Acc2, the lipid transport gene Cd36, and the lipid storage genes Cidea and Cidec were significantly elevated in AL mice while TRF showed reduced expression, reflecting lower steatosis in the liver." (PMID 38672595, 2024). "We have highlighted a possible mechanism involving the activation of LXR and its target genes, including the fatty acid transporter Cd36, which could explain the potentiating effect of TBT on PFOA-induced steatosis." (PMID 38891072, 2024). "Here we demonstrated that FASn and CD36 are the direct target genes of AP1, and Hcy activates it to induce their expressions, concurrently stimulating de novo FFA synthesis and uptake to promote hepatic lipid deposition and steatosis." (PMID 39117631, 2024). "Without hepatic STAT5, CD36 gene expression increased, resulting in augmented lipogenesis, fatty acid uptake, and steatosis." (PMID 36831184, 2023). "Hepatic CD36 is mainly regulated by nuclear receptors LXR, PXR and PPARγ in promoting steatosis." (PMID 36410795, 2023). "Mechanistically, the anti-steatosis effect of PEA may be due to the suppressed expression of ACC1 and CD36, elevated expression of PPAR-α, and the phosphorylation levels of AMPK." (PMID 34712137, 2021). "Under starvation conditions, we observed the hepatic lipid droplets of WT zebrafish larvae increased significantly, whereas the steatosis degree of cd36−/− mutants did not appear to have significant changes before and after starvation." (PMID 33513687, 2021). "Hepatocyte PPARγ and/or CD36 expression did not contribute to the development of steatosis induced by the MCD diet." (PMID 32411189, 2020). "The knockdown of CD36 contributes to improving lipid accumulation in the human hepatic cell line HepG2, suggesting that the liver-specific knockout of CD36 decreases hepatic lipid levels, increases FA oxidation (FAO), and reduces liver inflammatory markers in HF diet-induced steatosis." (PMID 32331364, 2020). "Western blot results showed that CD36 and SREBP-1c were significantly increased while PPARα decreased in db/db mice compared with that of db/m mice, indicating that hepatic steatosis was observed in db/db mice." (PMID 33551821, 2020). "Specifically, it has been proposed that the upregulation of PPARγ and CD36 in NAFLD might increase hepatic lipid uptake and promote the development of steatosis." (PMID 32411189, 2020). "Hepatic CD36 expression is increased in hepatocytes of mice fed the MCD diet, and it has been proposed that livers of mice fed a MCD diet take the excess fatty acids released by the white adipose tissue, and that leads to the development of steatosis." (PMID 32411189, 2020). "Our data also show that aging, in combination with HF-feeding, triggers the presence of CD36 at the cell surface of hepatocytes, which may contribute to enhanced fat uptake in NAFLD and drive the progression of simple steatosis towards NASH." (PMID 24751397, 2014). "The novelty of our present study is that both CD36 expression and the degree of steatosis are increased in livers from animal models of IH and in patients with OSA featured by nocturnal IH, supporting the notion that CD36 could be a key factor driving hepatosteatosis in OSA patients." (PMID 32850919, 2020). "Taken together, although PpargΔHep did not reduce the levels of plasma ALT nor steatosis, these data indicated that hepatocyte PPARγ and CD36 expressions could contribute to the upregulation of genes related to the progression of NASH." (PMID 32411189, 2020). "In the group of rats that were taking tomato juice (with and without steatosis), the genes involved in β-oxidation as well as the thrombospondin receptor (CD36) were positively regulated, and apolipoprotein B (APOB) and lipoprotein lipase (LPL) were negatively regulated." (PMID 31330977, 2019).
steatosis (continued). "Additionally, our data indicated that female SHROB rats elicited more efficient fatty acid transport (Cd36) and esterification (Pnpla3), and greater insulin sensitivity (higher phosphorylation of AKT and AMPK), all of which contributed to less severe steatosis." (PMID 30201044, 2018). "We could not detect any differences in fatty acid translocase CD36 mRNA expression in the liver between R-NC and R-HF groups at tihis time point that could explain the differences in steatosis." (PMID 30036374, 2018). "In contrast, the expression of Cd36, a fatty acids transporter, was significantly increased in the liver of mice treated with OSI-906 on day 7, but the increased expression had returned to the normal level by day 14, as reflected by the amelioration of steatosis." (PMID 28646158, 2017). "Although CD36 is known to facilitate long-chain fatty acid uptake and contributes to NAFLD progression, the mechanisms that link inflammatory stress to hepatic CD36 expression and steatosis remain unclear." (PMID 25048611, 2014). "Moreover, although not observed in basal conditions, a YBX1/CD36 positive feedback loop was observed in the in vitro model of steatosis, suggesting that lipid accumulation in MASLD may be a self-promoting process." (PMID 40959287, 2025). "Therefore, the sustained increased expression of CD36 in the liver may not be required for the progression of steatosis in mice with steatohepatitis." (PMID 32411189, 2020). "Still, abundant steatosis is not an immediate outcome of the highly increased expression level of PPARG, FABP4, CD36, and LPL in the liver of the severly obese minipigs." (PMID 32205840, 2020). "Real-Time PCR assayed on liver tissue demonstrated that the compound does not induce the expression of steatosis markers genes, FAS, SREBP1c, CD36 and PPARs." (PMID 28233865, 2017). "At the gene expression level, we found that the lipid transport gene Cd36 and the lipid storage genes Cidea and Cidec were elevated in the AL mice compared with NC, but were not elevated in the TRF group, consistent with the reduced steatosis." (PMID 33495474, 2021). "Hepatocyte-specific PPARγ and CD36 expression may not play a critical role in the development of steatosis induced by MCD diets, however, hepatocyte-specific PPARγ and CD36 may contribute to the progression of steatohepatitis in adult mice." (PMID 32411189, 2020).
diabetes (141 papers, 2005 to 2026). "Conversely, increasing CD36 acylation in healthy hearts recapitulates the increased CD36 S-acylation, membrane relocalization, and lipotoxic phenotype associated with diabetes." (PMID 40357580, 2025). "Our findings indicate that diabetes-induced APT1 deficiency promotes palmitoylated CD36 enrichment on plasma membranes through decreased APT1 expression, driving lipid overload and podocyte injury." (PMID 40607256, 2025). "Several predisposing factors for diabetes mellitus have been identified, including cluster determinant 36 (CD36) receptor expression." (PMID 36031603, 2022). "These diminishing effects of the CD36 polymorphism on sCD36 levels would be compensated for in subjects with type 2 diabetes mellitus." (PMID 36031603, 2022). "In humans, variants in the CD36 gene have been associated with lipid and glucose metabolism abnormality and altered susceptibility to metabolic syndrome and diabetes-associated coronary disease." (PMID 33995128, 2021). "Atherogenesis is highly associated with the process of fibrosis; therefore, increased CD36 expression has been described in diabetes cases and is thought to be associated with the pathogenesis of diabetic complications." (PMID 32626782, 2020). "The binding of long chain FFA to CD36 stimulates the tyrosine phosphorylation of downstream proteins, including proinflammatory response associated with diabetes." (PMID 30061862, 2018). "CD36, a fatty acid transporter, was previously shown to be associated with diabetes, while the role of LAPTM4B and RCOR1, significantly dysregulated in δ-cells, remains unclear and requires further investigation." (PMID 35885959, 2022). "CD36 (cluster of differentiation 36) is a membrane protein involved in lipid metabolism and has been linked to pathological conditions associated with metabolic disorders, such as diabetes and dyslipidemia." (PMID 34648514, 2021). "Recent studies have shown that in patients with diabetes, hyperglycemia can increase the expression of CD36, aggravate platelet-mediated inflammation, cause apoptosis of renal tubular epithelial cells and accelerate renal tubular degeneration and renal interstitial fibrosis." (PMID 34517817, 2021). "It has been shown that CD36 is involved in lipid metabolism and homoeostasis and has been linked to pathological conditions associated with metabolic disorders, such as obesity, insulin resistance, diabetes, dyslipidemia and atherosclerosis." (PMID 34648514, 2021). "Also, variants in the CD36 gene have been shown to increase susceptibility to the metabolic syndrome increasing risk for diabetes and cardiovascular disease." (PMID 26029481, 2013). "Taken together, these metabolic changes induced by inhibiting deacylation in control hearts recapitulate the metabolic phenotype of the T2D heart, indicating a critical role for CD36 S-acylation in the development of cardiac metabolic dysfunction in diabetes." (PMID 40357580, 2025). "In our other publication, we carefully described the function of CD36 in diabetes mellitus and its complications." (PMID 40565598, 2025). "Beyond the transcriptional activation of CD36 in diabetes, such as C/EBP, PXR, and LXR 14,16, the posttranslational regulatory mechanisms have garnered increasing attention." (PMID 40607256, 2025). "Inhibiting S-acylation decreases CD36 localization at the sarcolemma, correcting the excessive FA metabolism and improving contractile function in diabetes." (PMID 40357580, 2025). "Activation of the FoxO1 transcription factor in diabetes upregulates the transcription of the S-acylating enzyme zDHHC4, driving increased CD36 S-acylation and membrane relocalization." (PMID 40357580, 2025). "In cardiac injury related to diabetes, a positive feedback loop exists where high glucose rapidly induces CD36 protein, which in turn promotes further CD36 expression via microRNA-320 (miR-320) pathways." (PMID 41465460, 2025).